EGF (epidermal growth factor)
Diseases named in the same sentence as EGF in open-access papers (continued):
Sharing a sentence is not in itself a finding about the gene and the disease.
coronary artery disease (3 papers, 2013 to 2022). "The aim of this paper was to analyse the relationship between polymorphisms in the TGFB1, PDGFB, bFGF, EGF and VEGF-A genes and ISR in patients with stable coronary artery disease (SCAD)." (PMID 26930482, 2016). "By using Cytokine & Growth factors high-sensitivity array technology our study demonstrates that patients with stable coronary artery disease have significantly lower serum levels of vascular growth factors VGEF and EGF as well as of MCP-1 than healthy volunteers." (PMID 23984427, 2013).
cutaneous melanoma (3 papers, 1988 to 2021). A primary melanoma arising from atypical melanocytes in the skin. "Individuals with less than 10 (N = 127) or more than 100 (N = 128) benign nevi, and patients with cutaneous melanoma (N = 418) were investigated for the EGF +61A>G polymorphism, using an automated sequencing approach." (PMID 19624835, 2009). "This multifunctional system consists of gold nanoparticles coated with hyaluronic and oleic acids, and functionalized with epidermal growth factor for greater specificity towards cutaneous melanoma cells." (PMID 33808293, 2021).
cutaneous squamous cell carcinoma (3 papers, 2019 to 2024). "Moreover, in skin, the lncRNA MALAT1 was shown to interact with the transcription factor MYC and bind to the promoter region of the Kinectin 1 (KTN1) gene, thus contributing to enhancement of epidermal growth factor (EGF) signaling in cutaneous squamous cell carcinoma." (PMID 38542324, 2024).
cystic fibrosis (3 papers, 2008 to 2018). Autosomal recessive disorder caused by pathogenic variants in the CFTR gene (cystic fibrosis transmembrane conductance regulator), which encodes a chloride and bicarbonate channel expressed in epithelial cells, and follow the diagnosis criteria. "In Cystic fibrosis the excretion of an unusual, less effective form of salivary epidermal growth factor (EGF) was reported." (PMID 19424479, 2008).
epilepsy (3 papers, 2022 to 2025). A brain disorder characterized by episodes of abnormally increased neuronal discharge resulting in transient episodes of sensory or motor neurological dysfunction, or psychic dysfunction. "Some of the top protein differences between AD and epilepsy with the highest fold change from the correlation included increased MFGE8 (milk fat globule EGF and Factor V/VIII domain containing) by 2.5-fold in AD and decreased by 2.2-fold in epilepsy." (PMID 37521285, 2023).
gastric tumor (3 papers, 2017 to 2024). "We validated that in EGF-treated gastric tumor cells, RAF is inhibited by ERK feedback phosphorylation and this feedback loop is differentially regulated by Cav-1 in these two cell types." (PMID 29141593, 2017). "EGF protein expression was found in up to 88% of the gastric tumour samples, with most studies reporting EGF positivity in 29–58% of the cases." (PMID 27933395, 2017).
gout (3 papers, 2016 to 2022). A condition characterized by painful swelling of the joints, which is caused by deposition of urate crystals. "We observed a significant association between the T allele of EGF rs2298999 and gout (odds ratio = 0.77, 95% confidence interval = 0.67–0.88, Padjusted = 6.42 × 10−3)." (PMID 27506295, 2016). "Our results have shown that the EGF SNP rs2298999 is significantly associated with gout in the Han Chinese population and that one common EGF haplotype is associated with this disease." (PMID 27506295, 2016). "In summary, to the best of our knowledge, this study is the first to provide evidence of an association between EGF and gout in a Chinese Han population." (PMID 27506295, 2016). "Our results indicated that the carriers of the EGF rs2298999 TT genotype in the patient group were less susceptible to gout than the carriers of the CC genotype." (PMID 27506295, 2016). "We identified a significant association between the T allele (minor) of EGF rs2298999 and gout in our Chinese Han population (odds ratio (OR) = 0.77, 95% confidence interval (CI) = 0.67–0.88, Padjusted = 6.42 × 10−3)." (PMID 27506295, 2016). "A study in a male Chinese population linked rs2298999 of EGF gene with gout." (PMID 30123371, 2018). "MassArray system was used to genotype 93 tag SNPs in EGF and Elovl6 in an additional independent population of 1017 male gout patients and 1897 matched controls." (PMID 27506295, 2016). "Considering the biological function of EGF, we suggest that EGF is a potentially novel candidate gene for gout." (PMID 27506295, 2016). "Next, linkage disequilibrium (LD) analysis was used to investigate whether any EGF haplotype was correlated with gout." (PMID 27506295, 2016). "Emerging evidence suggests a key role of epigenetics in human inflammatory diseases; however, further study is needed to determine whether rs2298999 affects EGF transcription and whether these effects play a role in the development of gout." (PMID 27506295, 2016). "In the second stage of analysis, we performed fine mapping analysis of 93 tag SNPs in Elovl6 and in the epidermal growth factor gene (EGF) and its flanking regions in 1017 male patients gout and 1897 healthy male controls." (PMID 27506295, 2016).
Human papillomavirus infection (3 papers, 2021 to 2024). "Signal pathway analysis of tiRNA5-Lys-CTT-1 showed the tsRNA was involved in the pathway of Human papillomavirus infection, Senescence and Autophagy in Cancer, EGF/EGFR Signaling Pathway." (PMID 36845141, 2023). "These GS genes were mainly enriched in receptor tyrosine kinase signaling, MET signaling, human papillomavirus infection, PDGF signaling, the VEGFA–VEGFR2 signaling pathway, and the EGF–EGFR signaling pathway." (PMID 39766034, 2024).
hypospadias (3 papers, 2023). Hypospadias is the displacement of the urethral meatus on the ventrum of the penis. "A correlation between the low expression level of EGF, EGFR, and HOXA13 in the foreskin tissue and hypospadias cases indicates a possible cause of hypospadias." (PMID 37238140, 2023). "Several of these MeSH terms are associated with TF (transferrin), EGF (epidermal growth factor), MMP14 (Matrix metallopeptidase 14), CDH1 (Cadherin 1), and F13A1 (Coagulation factor XIII A chain) genes, related to CLJ and hypospadias." (PMID 37238140, 2023). "While these non-synonymous homozygous ADGRA2, EGF, F13A1, IRF6, and GSTP1 genes mutation might encode mutant proteins, they do not provide a prediction of the phenotype, but may contribute to more accurate assessments of the orofacial clefts or hypospadias." (PMID 37238140, 2023).
hypothyroidism (3 papers, 2021 to 2025). Abnormally low levels of thyroid hormone.
insulinoma (3 papers, 2011 to 2020). "Studies using recombinant EGF treatment demonstrate that EGF also increases insulin secretion in mouse insulinoma cells and pancreatic islets at 50% of the levels obtained with glucose." (PMID 32372975, 2020). "In the Min6 insulinoma cells the pattern changed, the BoT-Staple-EGF was as efficient as Bitox whereas CNTF and CRH moieties were less effective." (PMID 23638840, 2013). "Betacellulin (BTC), a member of the epidermal growth factor (EGF) family, was originally identified as a growth-promoting factor in the conditioned medium of a mouse pancreatic beta cell carcinoma (insulinoma) cell line." (PMID 21897861, 2011).
intestinal cancer (3 papers, 2019 to 2021). "In the intestinal cancer type, the family of fibroblast growth factors (FGFs) is strongly expressed, including the EGF (epidermal growth factor), TGF-α (transforming factor α), EGF-CFC (epidermal growth factor-CFC), and AR (amphiregulin)." (PMID 33167519, 2020).
Jaundice (3 papers, 2018 to 2022). Yellow pigmentation of the skin due to bilirubin, which in turn is the result of increased bilirubin concentration in the bloodstream. "Animal experiments have shown that EGF in breast milk can promote the growth and maturity of the liver and intestine, thus reducing the content of bilirubin in the blood and inhibiting the occurrence of jaundice." (PMID 36364849, 2022). "Breastmilk jaundice may occur due to certain factors present in human breastmilk (i.e., IL 1ß, IL6, ß-glucuronidase, epidermal growth factor, alpha-fetoprotein), which inhibits the conjugation of bilirubin that facilitates its excretion." (PMID 31440488, 2019). "It is speculated that the YCSND can treat jaundice by inhibiting the expression of c-jun, RELA, EGF, and EGFR." (PMID 30671125, 2018).
keratitis (3 papers, 2020 to 2025). A corneal disease that is characterized by inflammation of the cornea. "The corneal MN patch with LHAg NPs and EGF achieved the lowest clinical score on days 3, 5, or 7, reflecting the most effective therapeutic outcome for keratitis treatment." (PMID 39887635, 2025). "Three cases of keratitis (one of them diagnosed as filamentary keratitis) have also been described, suggesting the possibility to use the topical epidermal growth factor as an effective treatment for this corneal complication." (PMID 38254833, 2024).
LGL leukemia (3 papers, 2019 to 2024). "Comparing LGL leukemia to normal donor serum, three cytokines were significantly different after rigorous multiple testing correction: EGF was decreased and IP‐10 and G‐CSF were increased in LGL leukemia serum compared to normal donors." (PMID 32710512, 2020). "EGF was decreased while IP‐10 and G‐CSF were increased in LGL leukemia samples compared to normal donors." (PMID 32710512, 2020). "Analysis of LGL leukemia serum identified cytokines (EGF, IP‐10, G‐CSF) and sphingolipids (SMC22, SMC24, SMC20, LysoSM) that were significantly different compared to normal donors." (PMID 32710512, 2020). "On the other hand, epidermal growth factor (EGF) is decreased in LGL leukemia." (PMID 38610985, 2024). "It is currently unclear why LGL leukemia patients would have lower serum EGF." (PMID 32710512, 2020). "EGF, IP‐10, and G‐CSF were the top significant differences between LGL leukemia and normal donors." (PMID 32710512, 2020). "This strategy pinpointed seven cytokine and sphingolipid parameters (EGF, IP‐10, G‐CSF, SMC22, SMC24, SMC20, and LysoSM) that were significantly different between LGL leukemia subtypes and normal donor samples." (PMID 32710512, 2020). "The serum analyses identified cytokines (EGF, IP‐10, G‐CSF) and sphingolipids (SMC22, SMC24, SMC20, LysoSM) significantly different in the LGL leukemia group compared to normal donors." (PMID 32710512, 2020). "Taken together, we report that the cytokines EGF, IP‐10, and G‐CSF and the sphingolipids SMC22, SMC24, SMC20, and LysoSM are significantly different in LGL leukemia compared to normal donor serum." (PMID 32710512, 2020).
nasal polyps (3 papers, 2016 to 2024). "Our results suggest that the concentrations of epidermal growth factor and transforming growth factor-α in nasal secretions decrease after FESS in nasal polyposis patients." (PMID 38380493, 2024). "The current study investigates the expression profiles of EGF, EGFR and ERBB4 in patients with nasal polyps (NP), and their response to glucocorticosteroid (GC) treatment." (PMID 27285994, 2016). "In conclusion, this study has shown that treatment with the growth factor EGF upregulates the expression of MUC5AC in HNECs from CRSwNP via a pathway, which is likely to involve PI3K-TMEM16A signalling, and provides novel insights into the molecular mechanism of mucus hypersecretion in nasal polyps." (PMID 32514271, 2020).
nephritis (3 papers, 2022 to 2024). Inflammation of renal tissue. "Epidermal growth factor (EGF) concentrations are reduced in the urine of patients with active nephritis and are associated with severe renal outcomes, such as elevated serum creatinine levels and ESRD." (PMID 38255879, 2024). "In the US/Mexican cohort, patients with active LN had lower EGF than SLE patients without nephritis, whereas we did not observe any differences between groups." (PMID 35271583, 2022). "Unlike other potential biomarkers, EGF could be a useful biomarker for guiding treatment in LN that distinguishes kidney inflammation from systemic disease activity." (PMID 35271583, 2022).
nephrotic syndrome (3 papers, 2019 to 2021). A collection of symptoms that include severe edema, proteinuria, and hypoalbuminemia; it is indicative of renal dysfunction. "This study tests the association between baseline urinary epidermal growth factor (uEGF) excretion and longitudinal kidney function in children with nephrotic syndrome." (PMID 32280839, 2020). "In this study, the urinary profile of EGF excretion was mapped in children presenting with prolonged proteinuria or nephrotic syndrome refractory to or dependent of steroids." (PMID 34900856, 2021). "Pairing U EGF/uCreat assessment with biopsy in case of steroid-resistant nephrotic syndrome would, for example, be useful to identify false-negative biopsies that miss the FSGS lesion." (PMID 34900856, 2021).
neuroendocrine tumor (3 papers, 2013 to 2021). "Here, we investigated TNFα, CNTF, EGF, dermorphin, dynorphin 17, substance P, somatostatin, corticotropin-releasing hormone, and the native botulinum receptor-binding domain for their ability to direct the botulinum protease into a variety of neuroendocrine tumor cells." (PMID 23638840, 2013). "EGF and CNTF direct fusions were as active on the neuroendocrine tumor cells as the stapled products in terms of selectivity and cleavage of SNAP25." (PMID 23638840, 2013).
oligodendroglioma (3 papers, 2010 to 2015). A well-differentiated (WHO grade II), diffusely infiltrating neuroglial tumor, typically located in the cerebral hemispheres. "Yet, over the course of six months, these cells, even after two passages through mice, did not expand in suspension culture in serum free medium supplemented with FGF, and EGF and/or PDGFA, as has been previously reported for other oligodendroglioma and oligoastrocytoma cell populations." (PMID 23527265, 2013).
Parkinson’s (3 papers, 2014 to 2025). "Decreased levels of EGF in plasma have also been reported in Parkinson’s (PD) and AD, limiting in this way EGFR activation." (PMID 40508163, 2025).
Peri-Implantitis (3 papers, 2021 to 2025). An inflammatory process with loss of supporting bone in the tissues surrounding functioning DENTAL IMPLANTS. "The current study has limited evidence in terms of the association between EGF polymorphisms and peri-implantitis susceptibility, due to their small number of patients and lack of cross-ethnic comparisons." (PMID 34592884, 2021). "In summary, EGF rs2237051 polymorphism showed close association with the genetic background of peri-implantitis." (PMID 34592884, 2021). "In conclusion, this study preliminary proposed the relationship between EGF gene polymorphism and susceptibility to peri-implantitis, EGF rs2237051 mutation is associated with the occurrence of peri-implantitis." (PMID 34592884, 2021). "In the present study, two common SNPs of the EGF gene were selected, and their genetic association with the onset of peri-implantitis was explored." (PMID 34592884, 2021). "A close association was detected between EGF gene rs2237051 with peri-implantitis occurrence." (PMID 34592884, 2021). "EGF rs2237051 polymorphism was related to the genetic background of peri-implantitis." (PMID 34592884, 2021). "Consideringly, it was deduced that rs2237051 AA genotype may promote the expression level of EGF in cases that underwent dental implant, further contribute to inflammation and the risk of peri-implantitis." (PMID 34592884, 2021). "Therefore, in the present study, we explored the genetic association of EGF gene rs2237051 and rs4444903 polymorphisms with peri-implantitis risk in a Chinese Han population, in order to study the theoretical foundation for the mechanism of peri-implantitis." (PMID 34592884, 2021). "The qualitative evidence indicates that certain polymorphisms—particularly in the CD14, TNFα, IL-1, and EGF genes—show consistent associations with increased susceptibility to peri-implantitis, while others (e.g., MMP13, TGFB3, RANKL) demonstrate no clear relationships." (PMID 41373620, 2025). "However, the genetic association of EGF gene with Peri-implantitis has not been explored, which attracts our interest." (PMID 34592884, 2021).
Peritoneal Fibrosis (3 papers, 2017 to 2024). Disorder characterized by a wide range of structural changes in PERITONEUM, resulting from fibrogenic or inflammatory processes. "Since the EGF signaling pathway was shown to be involved in the progression of peritoneal fibrosis, we then studied EGF signaling activity after Fut8shRNA treatment." (PMID 33993842, 2021). "Since multiple signaling pathways are involved in the progression of peritoneal fibrosis and many key signaling proteins are modified by core fucosylation, we focused on the EGF signaling pathway in this study." (PMID 33993842, 2021). "However, our findings suggest that inhibition of core fucosylation of EGF receptor inactivates EGF signaling and ameliorates peritoneal fibrosis." (PMID 33993842, 2021). "Mesothelial cells may contribute to peritoneal fibrosis through their capacity for producing EGF and CTGF." (PMID 29179471, 2017). "Since the EGF signaling pathway plays a crucial role in the progression of peritoneal fibrosis, and the EGF receptor has been reported to be modified by core fucosylation, we designed the present study to observe the effects of core fucosylation of EGF receptor on peritoneal fibrosis." (PMID 33993842, 2021). "Previous studies showed that multiple signaling pathways were involved in the progression of peritoneal fibrosis, including transforming growth factor-β1 (TGF-β1), platelet-derived growth factor (PDGF), and epidermal growth factor (EGF) pathways." (PMID 33993842, 2021). "The mechanism may be that inhibition of core fucosylation of the EGF receptor inactivates the EGF signaling pathway by suppressing the phosphorylation of STAT3 and NF-κB in the peritoneal membrane of rats with peritoneal fibrosis, although further investigation is required." (PMID 33993842, 2021).
peritonitis (3 papers, 2013 to 2020). Inflammation of the peritoneum (tissue that lines the abdominal wall and covers most of the organs in the abdomen). "In culture, mesothelial cells can be further stimulated to produce ECM when exposed to peritoneal effluent from patients with acute peritonitis or various cytokines and growth factors such as IL-1β, TNF-α, epidermal growth factor (EGF), PDGF, and TGF-β." (PMID 26106328, 2015).